EGFR (epidermal growth factor receptor)
Diseases named in the same sentence as EGFR in open-access papers (continued):
Sharing a sentence is not in itself a finding about the gene and the disease.
non-small cell lung carcinoma (continued). "In this study, we report the results of Brazilian patients in stage IB-IIIA non-small cell lung cancer (NSCLC) following complete resection with minimal residual disease and EGFR mutations treated with adjuvant chemotherapy and/or EGFR-TKIs." (PMID 36629526, 2023). "EGFR mutant (EGFRm) metastatic non-small cell lung cancer (NSCLC) is generally sensitive to tyrosine kinase inhibitors (TKIs), considered the standard first line of treatment." (PMID 38322283, 2023). "EGFR can modulate autophagy in different models, such as non-small cell lung cancer, brain tumors, and keratinocytes." (PMID 37936170, 2023). "Mutations in epidermal growth factor receptor (EGFR) are found in 10–20% of Western patients and 40% of Asian patients with non-small-cell lung cancer (NSCLC)." (PMID 36765600, 2023). "For example, MerTK is involved in epidermal growth factor receptor (EGFR) inhibitor resistance in non-small-cell lung cancer, and blocking phagocytic receptors with the membrane-linked protein V can effectively slow tumor progression in prostate cancer." (PMID 37853449, 2023). "Genetic alterations in EGFR, IGFR, and anaplastic lymphoma kinase have already been linked to oncogenic transformation in non-small cell lung cancer (NSCLC)." (PMID 37813626, 2023). "The development of therapeutic agents targeting products of epidermal growth factor receptor (EGFR) gene mutation and anaplastic lymphoma kinase (ALK) rearrangements has improved survival in patients with non-small-cell lung cancer." (PMID 37835855, 2023). "EGFR amplification and EGFR over-expression are observed in many cancer types, including glioblastoma, non-small-cell lung cancer, and breast cancer." (PMID 38201434, 2023). "Combination of bevacizumab and erlotinib can prolong progression-free survival but not overall survival compared to erlotinib alone in advanced EGFR-mutant non-small cell lung cancer patients." (PMID 37635242, 2023). "EMERGING-CTONG 1103 showed improved progression-free survival (PFS) with neoadjuvant erlotinib vs. chemotherapy for patients harbouring EGFR sensibility mutations and R0 resected stage IIIA-N2 non-small cell lung cancer (NSCLC) (NCT01407822)." (PMID 36823150, 2023). "Afatinib monotherapy was approved by the US FDA for the first-line treatment of patients with EGFR-mutant, metastatic non-small-cell lung cancer (NSCLC) in July 2013." (PMID 36937848, 2023). "It has been reported that the increased secretion of IL-6 can induce resistance in non-small cell lung cancer cells to osimertinib, a third-generation EGFR-TKI." (PMID 37404767, 2023). "Reversible first-generation EGFR tyrosine kinase inhibitors (gefitinib and erlotinib) have clinically improved prognosis in patients with non-small-cell lung cancer (NSCLC), medullary thyroid carcinoma, and breast cancer." (PMID 37111769, 2023). "Epidermal growth factor receptor tyrosine kinase inhibitors (EGFR-TKIs) are an effective treatment for EGFR-mutant non-small cell lung cancer (NSCLC)." (PMID 37291533, 2023). "The proto-oncogenic role of EGFR has been established in several types of cancers, such as non-small-cell lung cancer (NSCLC), glioblastoma, squamous cell carcinoma of the head and neck, breast cancer, colorectal cancer, and pancreatic cancer." (PMID 37111291, 2023). "Afatinib is an FDA-approved irreversible blocker of the tyrosine kinase of the EGFR for treating advanced or metastatic non-small-cell lung cancer (NSCLC)." (PMID 37229243, 2023). "EGFR-TKI therapy represents a paradigm shift in the treatment of non-small cell lung cancer (NSCLC)." (PMID 37958300, 2023). "COL8A1 has been shown to promote non-small cell lung cancer progression by activating IFIT1/IFIT3-mediated EGFR signaling, while FABP5 can promote lymph node metastasis in cervical cancer by reprogramming fatty acid metabolism." (PMID 37795080, 2023).
non-small cell lung carcinoma (continued). "Currently, a phase II study looking at the efficacy and safety of MRG003 is ongoing in EGFR-positive advanced non-small cell lung cancer (NCT04838548)." (PMID 38107063, 2023). "Non-small-cell lung cancer (NSCLC) is a heterogeneous disease and, in approximately 20% of cases, characterized by oncogenic driver mutations in, e.g., EGFR, KRAS, and ALK." (PMID 36980795, 2023). "Liu established machine learning models based on CT images from diverse centers, proving their utility in assessing EGFR status in non-small cell lung cancer patients, with the RF model surpassing LR, DT, and SVM models." (PMID 38027000, 2023). "Patients with advanced non-small cell lung cancer (NSCLC) who are treated with epidermal growth factor receptor tyrosine kinase inhibitors (EGFR-TKIs) experience significant clinical benefits." (PMID 37841917, 2023). "The same is true for EGFR T790M non-small-cell lung cancer that is osimertinib-resistant with 6% of patients bearing ERBB2 amplification." (PMID 37359373, 2023). "For example, aberrant activation of EGFR in non-small-cell lung carcinoma (NSCLC) drives UDP-glucose 6-dehydrogenase (UGDH) phosphorylation and activation." (PMID 37835497, 2023). "Currently, the EGFR inhibitor gefitinib is a first-line intervention for patients with advanced non-small cell lung cancer (NSCLC), but a prevalent problem is the occurrence of TKI resistance." (PMID 37954979, 2023). "Gefitinib, Erlotinib, Lapatinib, Trametinib, Afatinib, and Osimertinib are tyrosine kinase inhibitors, that have been used in the treatment of non-small cell lung cancer and all of which target EGFR." (PMID 38074121, 2023). "The clinical outcomes of untreated patients with advanced non-small cell lung cancer in the EGFR+/METamp+ group were compared to those in the EGFR+/METamp- group." (PMID 37941550, 2023). "The representative FDA-approved EGFR inhibitor gefitinib (the brand name Iressa) is a medication used for non-small cell lung cancers." (PMID 37239373, 2023). "NK1R also promotes non-small cell lung cancer progression through transactivation of EGFR phosphorylation and regulating the intracellular signaling of Extracellular Signal-Regulated Kinase 1/2 (ERK1/2) and Protein Kinase B (Akt)." (PMID 36986466, 2023). "Consistent with the potential of EHD1 expression in fact regulating the RTK traffic in tumors, EHD1 levels in non-small cell lung cancer correlated with EGFR expression and specified shorter survival, metastasis, and chemotherapy resistance." (PMID 37474760, 2023). "A 43-year-old female patient diagnosed with advanced non-small cell lung cancer with bone metastasis harbored the EGFR exon 19 deletion and received the treatment of erlotinib, and the mass of the right lung tumor was reduced after about 2 months of treatment." (PMID 37567953, 2023). "In this study, we aimed to investigate the prevalence and details of OBR and its association with clinical outcomes in patients with epidermal growth factor receptor (EGFR)-mutant non-small cell lung cancer (NSCLC) treated with osimertinib." (PMID 37674153, 2023). "Key players in these pathways include EGFR, PI3K, Akt, mTOR, and PTEN, which are commonly mutated in lung cancer, and are found to be upregulated by morphine via MOR in non-small-cell lung cancer." (PMID 36835812, 2023). "Cetuximab and Panitumumab are FDA-approved mAbs against EGFR, and Erlotinib and Gefitinib are EGFR-TKIs first-line therapies for patients with non-small cell lung cancer (NSCLC)." (PMID 37895906, 2023). "Immunohistochemical detection of EGFR is a well-established technique in non-small-cell lung cancer." (PMID 35663041, 2022). "Further increased YAP nuclear localization has also been reported to be associated with chemotherapy resistance and relapse in EGFR-mutant, KRAS-mutant and B-RRAF mutant, ALK-rearranged non-small-cell lung cancer and RAS-driven neuroblastoma." (PMID 36523977, 2022).
non-small cell lung carcinoma (continued). "Results from a phase I trial using PB-generated anti-EGFR CAR T in R/R advanced non-small cell lung carcinoma (NSCLC) were recently published." (PMID 35757746, 2022). "In non-small cell lung cancer (NSCLC), however, the clinical utility of ctDNA has been limited to detecting mutations in the genes that encode druggable proteins such as epidermal growth factor receptor (EGFR) and anaplastic lymphoma kinase (ALK)." (PMID 36076922, 2022). "Afatinib targeted therapy has a significant clinical intervention effect on patients with non-small-cell lung cancer, which not only helps to improve the immune function of patients but also effectively improves the serum EGFR and pro-GRP levels of patients." (PMID 36157204, 2022). "The epidermal growth factor receptor (EGFR) and ERBB tyrosine kinase inhibitor Afatinib has been used as a first-line drug for non-small cell lung cancer patients with an EGFR mutation." (PMID 36733386, 2022). "Recent research has shown that non-small-cell lung carcinomas with acquired resistance to EGFR inhibitors tend to show amplifications in MET." (PMID 35069735, 2022). "In this study, enriched cancer-associated fibroblasts (CAFs) were observed in tumor tissues isolated from epidermal growth factor receptor tyrosine kinase inhibitors (EGFR TKIs) resistant non-small cell lung cancer (NSCLC) patients." (PMID 35831824, 2022). "Compared to tons of EGFR inhibitors studied as ABCB1 reversal agents, MRTX849 showed good anticancer efficacy and safety in patients with non-small cell lung cancer and colorectal cancer with KRAS G12C mutation in clinical studies." (PMID 36104708, 2022). "Epidermal growth factor receptor (EGFR) is reported as an important driver oncogene in non-small cell lung cancer (NSCLC)." (PMID 35303882, 2022). "In malignant pleural mesothelioma and non-small cell lung cancer, miR-16 mimic was packaged in minicells targeted with epidermal growth factor receptor (EGFR)-specific antibodies, which exhibited an acceptable safety profile in a phase I study (NCT02369198)." (PMID 35081965, 2022). "Treatment options for metastatic EGFR mutant non-small cell lung cancer (NSCLC) have increased during the past two decades." (PMID 35785671, 2022). "Other research showed that a concentration-dependent dose reduces EGFR phosphorylation by inducing EGFR degradation and suppressing cell proliferation in various gefitinib-resistant non-small-cell lung carcinoma cell lines." (PMID 35956419, 2022). "Adenocarcinoma comprises 80% of non-small cell lung cancer (NSCLC), and epidermal growth factor receptor (EGFR) mutations mostly appear in this subtype." (PMID 36052262, 2022). "And the downregulation of GSDMD was found to attenuate tumor proliferation via the intrinsic mitochondrial apoptotic pathway and inhibition of EGFR/Akt signaling and predicted a good prognosis in non-small cell lung cancer." (PMID 36138348, 2022). "Cutaneous toxicities induced by anti-EGFR therapy, in particular rash, are the most frequent adverse effects observed in patients with EGFR-mutant cancers, including non-small cell lung cancer, breast cancer and colorectal cancer." (PMID 35324426, 2022). "Epidermal growth factor receptor (EGFR) is an intensively focused target for anti-tumor compounds used in non-small cell lung cancer (NSCLC) therapy." (PMID 35744964, 2022). "Five years later, Petrulli and coworkers showed that, among subjects with non-small-cell lung cancer (NSCLC) and various epidermal growth factor receptor mutations, the kinetic properties of the tracer varied substantially." (PMID 35563414, 2022). "In this study, patients with advanced non-small cell lung cancer (NSCLC) with EGFR/ALK wild type (WT) and PDL1 expression ≥ 1%, according to tumor proportion (TPS) score, received the combination of tiragolumab plus atezolizumab vs. atezolizumab alone." (PMID 36077813, 2022).
non-small cell lung carcinoma (continued). "EGFR and Wnt/β-catenin signaling pathways play a prominent role in tumor progression in various human cancers including non-small-cell lung carcinoma (NSCLC)." (PMID 35744950, 2022). "Encouragingly, the EGFR-mutant NCI-H1975 non-small cell lung carcinoma cell line turned out to be more sensitive to the treatment with the obtained complexes." (PMID 35203671, 2022). "EGFR inhibitors such as monoclonal antibodies or small molecule TKIs have been approved for the therapy of non-small cell lung cancer, head and neck squamous cell carcinoma, and colorectal cancers." (PMID 34991599, 2022). "Osimertinib is active against T790M-positive epidermal growth factor receptor mutant non-small cell lung cancer." (PMID 35323965, 2022). "These drugs are considered as the representative targeted therapy against solid tumors such as non-small-cell lung cancer (NSCLC) with kinase domain mutations, which show great response to EGFR TKIs." (PMID 36438839, 2022). "Erlotinib, as an inhibitor of the tyrosine kinase receptor EGFR, is used to treat non-small cell lung cancer and pancreatic cancer." (PMID 35568782, 2022). "EGFR mutations in non-small cell lung cancer (NSCLC) are associated with a poor response to immune checkpoint inhibitors (ICIs), and only 20% of NSCLC patients harboring EGFR mutations benefit from immunotherapy." (PMID 36229854, 2022). "Blocking signaling by epidermal growth factor receptor (EGFR), can effectively inhibit the proliferation and differentiation of non-small-cell lung cancer (NSCLC)." (PMID 35242698, 2022). "The combination of apigenin and gefitinib on epidermal growth factor receptor (EGFR)-resistant mutant non-small cell lung cancer was evaluated." (PMID 36144783, 2022). "The detection of mutations in the kinase domain of the epidermal growth factor receptor provides guidance for advanced non-small cell lung cancer, and EGFR tyrosine kinase inhibitors are the standard first-line therapy." (PMID 36291877, 2022). "For example, several EGFR inhibitor-based approaches are currently used to treat patients with EGFR-positive tumors, notably non-small cell lung cancer." (PMID 35912242, 2022). "Dysregulated epidermal growth factor receptor (EGFR) expression is frequently observed in non-small cell lung cancer (NSCLC) growth and metastasis." (PMID 35408854, 2022). "Advanced EGFR mutant non-small cell lung cancers are now treated with EGFR tyrosine kinase inhibitors as standard of care." (PMID 35368709, 2022). "In turn, Cu(II)-complexes were evaluated for their anticancer properties against A549 cells, as well as NCI-H460 non-small cell lung carcinoma cells and EGFR-mutant NCI-H1975 non-small cell lung carcinoma cells." (PMID 35203671, 2022). "The bsAb Amivantamab targeting mesenchymal transition factor (MET) and epidermal growth factor receptor (EGFR) was developed using this platform for the treatment of advanced non-small cell lung cancer." (PMID 36341333, 2022). "As the most prevalent molecular mutation subtypes in non-small cell lung cancer (NSCLC), EGFR-TKIs are currently a standard first-line therapy for targeting the mutated EGFR in advanced NSCLC patients." (PMID 35444951, 2022). "Researchers also found that in non-small cell lung cancer, EGFR-mutant and ALK-rearranged tumors responded poorly to anti-PD-1/PD-L1 treatment and exhibited higher infiltrations of CD4+ memory resting T cells." (PMID 36588538, 2022). "MYF-01-37 binds covalently to TEAD and disrupts the YAP-TEAD interaction, enhances EGFR inhibitor-mediated apoptosis, and prevents dormancy in EGFR-mutant non-small cell lung cancer." (PMID 36294681, 2022). "Although anti-EGFR CAR-T cells are effective against non-small cell lung cancer and biliary cancer, several clinical trials suggest that CAR-T cells have a lower activity against solid tumors." (PMID 36551506, 2022).
non-small cell lung carcinoma (continued). "The EGFR tyrosine kinase inhibitor osimertinib was recently approved for resected EGFR-mutant stage IB-IIIA non-small cell lung cancer due to evidence of improved disease-free survival." (PMID 35285487, 2022). "Targeted therapies, represented by epidermal growth factor receptor-tyrosine kinase inhibitors (EGFR-TKIs), have greatly improved the quality of life and prognosis of patients with non-small cell lung cancer (NSCLC)." (PMID 36358728, 2022). "Epidermal growth factor receptor (EGFR) is a canonical therapeutic target for non-small cell lung cancer, breast cancer, and colorectal cancer." (PMID 35324426, 2022). "However, recent studies have indicated that the clinical outcomes of non-small-cell lung cancer patients with EGFR mutations are promising and that patients with different EGFR mutations may experience different outcomes of ICI therapy despite their generally low response to ICIs." (PMID 35371031, 2022). "When the expression of KL-6 in the serum and tumour tissue of patients with non-small cell lung cancer is increased, they have a poor prognosis and worse curative effect of EGFR-TKIs." (PMID 36050683, 2022). "A recent study showed that programmed death-ligand 1 (PD-L1) expression and T-cell infiltration in patients with EGFR–mutant non-small cell lung cancer are related to immunotherapy." (PMID 35903358, 2022). "As a result, nuclear EGFR has prognostic value for a variety of cancers, including breast and non-small cell lung cancer." (PMID 36054194, 2022). "Those inhibitors have good anti-proliferative effects against breast cancer (MCF-7), hepatocellular carcinoma (HepG-2), colorectal carcinoma (HCT-116), and non-small cell lung cancer cells (A549) and exhibited EGFR inhibitory action." (PMID 35470756, 2022). "Osimertinib is a third-generation EGFR tyrosine kinase inhibitor approved for metastatic EGFR-mutant non-small cell lung cancer, hence representing a possible option to treat PeCa in the second-line setting as a concept of drug repurposing." (PMID 35406455, 2022). "Therapeutic responses of non-small cell lung cancer (NSCLC) to epidermal growth factor receptor (EGFR) - tyrosine kinase inhibitors (TKIs) are known to be associated with EGFR mutations." (PMID 36376325, 2022). "We used the CCM-CTCD to study 30 non-small cell lung cancer (NSCLC) patients, with documented EGFR mutations in their tumor tissues." (PMID 35664056, 2022). "CAGE conferred resistance to epidermal growth factor receptor (EGFR)-TKIs (EGFR tyrosine kinase inhibitors) by promoting autophagy via binding to Beclin1 in non-small cell lung cancer cells." (PMID 35682560, 2022). "Many medications are permitted alone or in combination with chemotherapy for colorectal cancer, non-small-cell lung cancer, and breast cancer due to the success of EGFR-targeting in the treatment of cancer." (PMID 36457709, 2022). "In the latest national comprehensive cancer network (NCCN) guidelines of non-small cell lung cancer, gefitinib, erlotinib, afatinib, dacomitinib, and osimertinib are all category 1 recommended EGFR TKIs." (PMID 36422186, 2022). "A mitochondrial pool of EGFR has recently been described in regulating mitochondrial fission and promoting metastasis in non-small cell lung cancer cells." (PMID 35356277, 2022). "The EGFR inhibitor erlotinib has been used as a monotherapy for patients with non-small cell lung cancer (NSCLC) and combined with gemcitabine for patients with pancreatic cancer to prolong their survival." (PMID 35851575, 2022). "The activation of the hedgehog (Hh) signaling mediated the resistance of non-small cell lung cancer cells to EGFR-TKIs (gefitinib, afatinib, and osimertinib)." (PMID 35682560, 2022).